ALB (albumin)
Diseases named in the same sentence as ALB in open-access papers (continued):
Sharing a sentence is not in itself a finding about the gene and the disease.
diabetic nephropathy (continued). "However, studies show that the urinary albumin concentration in a random spot urine is a reliable predictor of diabetic nephropathy and cardiovascular events." (PMID 29568334, 2018). "In this study, diabetic kidney disease was diagnosed based on urinary albumin excretion alone." (PMID 29910771, 2018). "The results of one study from Guanzhou showed that TCM decoction with wind-medicines could significantly decrease the urinary albumin excretion rate and urine albumin-to-creatinine ratio in III phase diabetic kidney disease patients (1984 Mogensen staging)." (PMID 29552086, 2018). "However, early-stage diabetic kidney disease was defined as urinary albumin excretion within the microalbuminuria range only." (PMID 29910771, 2018). "By doing so, we demonstrate suPAR to be an independent predictor for the onset of microalbuminuria as a key indicator and progression factor of diabetic nephropathy and to consistently correlate to the magnitude of urinary albumin excretion in manifest disease." (PMID 28091558, 2017). "Albuminuria is widely used to indicate early phases of diabetic nephropathy although it is limited by the fact that structural damage might precede albumin excretion." (PMID 28577020, 2017). "Furthermore a third recent study from Taiwan investigated the correlation of full-length betatrophin with urinary albumin excretion and eGFR as markers of diabetic nephropathy in patients suffering from type 2 diabetes." (PMID 28257453, 2017). "More recently, attention has been focused on the use of persistent microalbuminuria to define the presence of incipient diabetic nephropathy and initial work on microalbuminuria attributed excretion of >30 mg/day of albumin in urine to increased glomerular filtration of albumin." (PMID 28250988, 2017). "We determined the albumin/creatinine ratio (ACR) to assess progression of diabetic nephropathy." (PMID 28281693, 2017). "Furthermore, the early diagnosis of albumin excretion related to glomerular permeability is contributed to the clinical predictor of renal function in diabetic nephropathy." (PMID 28662169, 2017). "However, comparison between high-flux and low-flux membranes in a randomized controlled trial reported better prognosis with the use of high-flux membranes for hemodialysis patients with diabetic nephropathy and patients with serum albumin <4.0 g/dL." (PMID 28910324, 2017). "In conclusion, the present study demonstrated that DPP-4i treatment could ameliorate diabetic nephropathy, by reducing urine albumin excretion and mitigating the reduction of eGFR in T2DM patients." (PMID 28119930, 2016). "The rise in miR-451-5p may be a more sensitive predictor of imminent diabetic kidney disease, as compared to albumin excretion." (PMID 27101382, 2016). "Also recently serum miR-21 was suggested as a marker for diabetic nephropathy, and positive correlation between miR-21 and urine albumin creatinine ratio or content of collagen fibers has been demonstrated." (PMID 27610006, 2016). "The onset of elevated levels of urinary albumin excretion is an early sign of diabetic nephropathy." (PMID 25717442, 2015). "In this line, a pooled analysis of interventional studies has demonstrated that the initial percentage decrease in albumin excretion rate was 20.8% in T2DM with late diabetic nephropathy (macroalbuminuria) and the corresponding annual percentage rate of decline in GFR was 9.2%." (PMID 25856231, 2015). "We investigated the relationship between the glycemic indices glycated albumin (GA) and glycated hemoglobin (HbA1c) and the progression of diabetic vascular complications [diabetic nephropathy (DN) and carotid artery atherosclerosis (CAA)] in subjects with type 1 diabetes (T1D)." (PMID 25975731, 2015). "TZDs reduce urinary albumin excretion and proteinuria in diabetic nephropathy." (PMID 26083376, 2015). "Thiazolidinediones (TZDs) reduce urinary albumin excretion and proteinuria in diabetic nephropathy." (PMID 26083376, 2015).
diabetic nephropathy (continued). "Finally, a multivariate Cox regression revealed that baseline estimated GFR, proteinuria, albumin, diabetic nephropathy, LDL-C, age, Na-Cl and use of RASi were statistically significant in the descending order of Wald statistic (Model 1)." (PMID 26177463, 2015). "Except for AGE-RAGE, heparanase is another target gene of the diabetic nephropathy mediators albumin and AGE, which was proved by experimental evidence to play a key role in AGEs-induced macrophage migration associated with inflammation in diabetic vascular complication." (PMID 25391642, 2014). "We found that empagliflozin exerts protective effects against diabetic nephropathy, as shown by the reduction of urinary albumin excretion, glomerular sclerosis index, glomerular macrophage infiltration, and glomerular superoxide in db/db mice with empagliflozin." (PMID 25344694, 2014). "First, ACR was not measured directly but rather derived from 24-hour urine protein excretion using a relationship observed between ACR and 24-hour protein excretion in the IDNT study, a study of diabetic nephropathy, where albumin is the predominant urinary protein." (PMID 23803596, 2013). "Diabetic nephropathy is a clinical manifestation of developed microalbuminuria that may be due to impaired tubular reabsorption and/or leakage of albumin due to injured glomeruli that may leads to alteration of selective barriers of glomeruli." (PMID 23409091, 2013). "Manifestations of urinary albumin progressed from normoalbuminuria to microalbuminuria at an annual rate of 2.0%, from microalbuminuria to macroalbuminuria at 2.8% annually, and from macroalbuminuria to diabetic nephropathy at 2.3% annually." (PMID 23570327, 2013). "We next investigated the urine albumin leakage, early markers of diabetic nephropathy." (PMID 22848482, 2012). "In addition to the increase in urinary albumin excretion, one of the most remarkable renal pathological findings in diabetic nephropathy is mesangial expansion due to pathological accumulation of extracellular matrix (ECM) components in glomeruli." (PMID 21837246, 2012). "Thus, it is necessary to determine the presence of new-onset CKD employing urinary albumin measurement in participants with diabetic nephropathy during the early stage." (PMID 21722384, 2011). "Diabetic nephropathy is graded according to the urinary albumin excretion rate (UAE)." (PMID 20470427, 2010). "Diabetic nephropathy screening is made by measuring albumin in spot urine." (PMID 19825147, 2009). "Characterized by an ongoing deterioration in renal capabilities, diabetic nephropathy is marked by ongoing leakage of small amounts of albumin in the urine, a decline in the Glomerular Filtration Rate, and a heightened ratio of urinary albumin to creatinine levels." (PMID 40458807, 2025). "Also, patients with a lower 3MS score had older age, a shorter duration of dialysis, a higher proportion of diabetic kidney disease, a higher proportion of prior stroke, a lower education level, a lower diastolic blood pressure, and a lower serum albumin level." (PMID 39519609, 2024). "Firstly, IR is associated with increased glomerular hydrostatic pressure and urinary albumin excretion, which was proved to result in the incidence of early glomerular hyperfifiltration and contribute to late glomerular damage in the early stages of diabetic nephropathy." (PMID 37653418, 2023). "Furthermore, a cross-sectional study from Singapore showed that a number of short acylcarnitines including their dicarboxylic derivatives (C2-C6) were elevated in diabetic kidney disease, in particular, C4 was a positive, independent, and significant predictor of the albumin/creatinine ratio levels." (PMID 37330521, 2023). "Diabetic kidney disease (DKD), also known as diabetic nephropathy (DN), is defined as an increase in urine albumin excretion or a decrease in the glomerular filtration rate (GFR) or both." (PMID 36831005, 2023).
diabetic nephropathy (continued). "Similarly, SIRT1 transgenic mice demonstrate ameliorated diabetic kidney disease (DKD) because of reduced levels of oxidative stress markers, while induced SIRT1-deficient mice show elevated kidney inflammation and urinary albumin excretion." (PMID 35277012, 2022). "Diabetic nephropathy leads to enhanced albumin leak into the initial urine by (a) glomerular hyperfiltration and increased trans-glomerular pressure, and (b) by structural and functional changes at the filtration barrier, permeating albumin leak into Bauman’s capsule." (PMID 36139492, 2022). "Furthermore, 30% of patients with diabetic kidney disease have normal urine albumin levels." (PMID 35455664, 2022). "Thus, diabetic nephropathy may be concealed if filtered albumin is fully reclaimed and degraded, although overt albuminuria reflects glomerular leak of albumin beyond the tubular reabsorptive capacity." (PMID 35257085, 2022). "Recently, a meta-analysis consisting of 12 randomized controlled trials (RCTs) and involving 911 patients revealed that the BHD could be an adjunct therapy with RAAS inhibitors for early diabetic nephropathy patients by reducing the 24 h urine albumin excretion rate (UAER)." (PMID 34775979, 2021). "However, when inheritance models were applied and adjusted for diabetic nephropathy and serum albumin concentration, the rs854560 AA + AT genotypes (P = 0.036) and the rs705379 CT + CC genotypes (P = 0.045) were more frequent in HCV susceptible individuals than the T genotype." (PMID 34445971, 2021). "This study reveals that after eight weeks of CrPic administration, serum creatinine, BUN, and urinary albumin all significantly decreased in the CrPic-treated group, compared to the DN group, thus indicating that CrPic has a protective effect on renal function in diabetic nephropathy rats." (PMID 32143429, 2020). "However, several facts may support this idea, Amadori-albumin has been demonstrated in the glomeruli of patients with diabetic nephropathy, and the degree of staining was increased with the severity of tissue damage." (PMID 32630324, 2020). "More recently, ROC studies among type 2 DM groups divided according to albumin : creatinine ratio have established optimum cut-off values of uVDBP to be between 550 and 553 ng/mg that correspond to >90% sensitivity and >83% specificity for early detection/diagnosis of diabetic nephropathy." (PMID 29888290, 2018). "Moreover, it has been proposed that tubular injury could precede glomerular injury in diabetic nephropathy, which may explain the early appearance of an increase in several urinary biomarker excretion compared with albumin." (PMID 25884625, 2015). "Thus, it may serves as early marker for tubular damages in diabetic nephropathy and may precede albumin excretion to the urine." (PMID 24143207, 2013). "At present MIC is used as the best risk marker for development of diabetic nephropathy; however, the number of patients with MIC that progress to DMN is less in recent studies compared to previously, and some even regress to normoalbuminuria (N)(U-albumin<30 mg/24 h)." (PMID 20205888, 2010). "B: There was significantly reduced urinary albumin excretion, urinary TGF-β1 levels, and type IV collagen, suggesting a reduction in the progression of diabetic nephropathy." (PMID 40062098, 2025). "Improvements in urinary albumin, creatinine, and the albumin-to-creatinine ratio further support DNR’s potential to mitigate key pathological features of diabetic nephropathy." (PMID 41155478, 2025). "The heatmap for the diabetic nephropathy group shows a consistent pattern of positive correlations between AOPP and multiple inflammatory indices after controlling for age, sex, and albumin." (PMID 41226704, 2025).
diabetic nephropathy (continued). "Diabetic kidney disease (DKD) is traditionally diagnosed based on estimated glomerular filtration rate (eGFR) and albuminuria, defined as a persistent urinary albumin-to-creatinine ratio of ≥30 mg/g and/or a sustained eGFR decline below 60 ml/min per 1.73 m2." (PMID 40370868, 2025). "Diabetic nephropathy (DN) or diabetic kidney disease (DKD) is a disorder characterised by persistent albuminuria (excretion of pathological quantities of urine albumin), diabetic glomerular lesions, a progressive decline in the glomerular filtration rate, and elevated arterial blood pressure." (PMID 41179869, 2025). "Diabetic Kidney Disease (DKD), a common microvascular complication of type I and type II diabetes, is characterized by increased albuminuria level or urinary albumin-to-creatinine ratio (UACR), decreased glomerular filtration rate (GFR) or both." (PMID 39626591, 2024). "In the same way, a study reported a reduction in urinary albumin to creatinine ratio and decreased serum creatinine related to kidney injury improvement by MCC950 treatment in a mice model of diabetic nephropathy." (PMID 38114914, 2023). "In our results, serum albumin concentration accompanied by elevation of serum BUN and creatinine concentrations confirmed the incidence of diabetic kidney diseases induced with STZ." (PMID 36984840, 2023). "Similarly, in the present study, a linear correlation was identified between urinary albumin excretion levels and periodontal disease inflammatory levels, suggesting a significant role of periodontal pathogen-induced pro-inflammatory systemic markers in the progression of diabetic nephropathy." (PMID 37809241, 2023). "Disrupted serum calcium and urine albumin excretion are considered as modifiable risk factors for CKD progression that may help in early preventive measures serum calcium is tightly linked to altered vitamin D3 and intact PTH levels in patients with DM and diabetic nephropathy." (PMID 37312131, 2023). "An early diagnosis of diabetic kidney disease (DKD) involves finding some biomarkers besides eGFR and levels of urinary albumin and creatinine ratio." (PMID 37371622, 2023). "TNF-α inhibition with infliximab and FR167653 decreased urinary albumin excretion, suggesting the role of TNF-α in the pathogenesis of diabetic nephropathy, with TNF-α inhibition is a potential therapeutic strategy." (PMID 35328704, 2022). "The urine albumin creatinine ratio (UACR) is also used in addition to the estimated glomerular filtration rate (eGFR), to classify diabetic kidney disease into three categories: A1 (<3 mg/mmol), A2 (3-30 mg/mmol), and A3 (>30 mg/mmol)." (PMID 34909290, 2021). "In diabetes nephropathy, ADC values positively correlated to eGFR values, inversely to clinical stages and urinary albumin excretion." (PMID 34187388, 2021). "However, as it has already been discussed, megalin levels are reduced under fibrosis-associated conditions, i.e. diabetic nephropathy and gallstone disease, ageing and cancer, by mechanisms that are likely to involve TGF-ß as well as other molecules/mechanisms, including Ang II, leptin and albumin." (PMID 31120873, 2019). "As a screening index of diabetic kidney disease (DKD), urinary albumin/creatine ratio (UACR) is commonly used." (PMID 31637265, 2019). "Serum creatinine (SCr), eGFR and urinary albumin-to-creatinine ratio (UACR), have been investigated using GWAS in different aetiologies of CKD and ESRD, such as diabetic kidney disease (DKD), MGN and IgAN." (PMID 30359254, 2018). "In a recent study among patients with diabetic nephropathy receiving an ACEi or an ARB, the addition of finerenone compared with placebo resulted in improvement in the urinary albumin-creatinine ratio." (PMID 30356804, 2018). "As for diabetic kidney disease, meta-analysis suggested that DHI can improve urinary albumin excretion rate (UAER) levels in patients." (PMID 29849705, 2018).
diabetic nephropathy (continued). "The diabetic nephropathy group had a significantly higher UACR and a significantly lower serum albumin level." (PMID 26839894, 2016). "A stratified Cox regression showed the highest hazard ratio (HR) at TA-P 3.4 mg/dL (HR 17.60, 95% CI 3.92–78.98) adjusted for baseline covariates such as sex, age, diabetic nephropathy, estimated GFR, serum albumin, Na-Cl, phosphorus, LDL-C and proteinuria." (PMID 27123981, 2016). "Diabetic nephropathy was characterized by higher blood pressure and UACR and lower age, eGFR, and serum albumin levels compared with nephrosclerosis at RRT initiation." (PMID 26839894, 2016). "Then, the multivariate Cox regression analysis adjusted for sex, age, diabetic nephropathy, estimated GFR, albumin, Na-Cl, phosphorus, LDL-C and proteinuria showed that the highest HR was also at the threshold of TA-P 3.4 mg/dL." (PMID 27123981, 2016). "Urinary TNF-α levels were also elevated in diabetic patients with increased urinary albumin excretion and there was a significant rise in urinary TNF-α excretion as diabetic nephropathy progressed." (PMID 26239462, 2015). "Regressors were characterized by a lower prevalence of diabetic nephropathy and PKD, lower BP, proteinuria and serum phosphate and higher serum albumin and hemoglobin." (PMID 26462071, 2015). "A standard multivariate Cox regression analysis was performed in the stepwise manner; baseline estimated GFR, proteinuria, albumin, Na-Cl, sex (male), age, phosphorus, LDL cholesterol and diabetic nephropathy were extracted as independent predictors of ESRD." (PMID 26700005, 2015). "In general, the increase in urine albumin, and the decrease in estimated GFR represent severe or aggravated renal function in patients with diabetic nephropathy." (PMID 25884625, 2015). "Thus, TNF-α inhibition decreased urinary albumin excretion in diabetic rats, as indicated by the reduction in 24 h urinary albumin/creatinine ratio (Ualb/Ucr), thereby suggesting that it might be a potential therapeutic strategy for diabetic nephropathy." (PMID 24177571, 2013). "To examine early change of the kidney in diabetic nephropathy, we employed STZ induced diabetic model and examined the blood glucose and urinary albumin level at 2, 4, 6, 8 and 12 weeks after injection of STZ." (PMID 23560927, 2013). "Nutrition-related parameters such as mean levels of serum albumin, BUN, and creatinine were lower in the diabetic nephropathy group than in the other groups." (PMID 15930806, 2005). "The relationship between neutrophil percentage to albumin (NPAR) index and mortality in patients with diabetic kidney disease (DKD) remains unclear." (PMID 41650096, 2026). "In an experimental model of diabetic nephropathy, rubositoline has been shown to normalize glomerular hyperfiltration by inhibiting PKC-β, reduce urinary albumin excretion, maintain renal function, and mitigate mesangial dilation, glomerular sclerosis, and tubulointerstitial fibrosis." (PMID 40230860, 2025). "This study aimed to evaluate the effects of autologous dendritic cell (DC) immunotherapy on clinical outcomes (glomerular filtration rate/GFR and urine creatinine albumin ratio/UACR) and endothelial dysfunction (ICAM, VCAM, VEGF) in patients with diabetic kidney disease (DKD)." (PMID 39852146, 2025). "Patients did not have signs of diabetic kidney disease: plasma creatinine, estimated glomerular filtration rate, and urinary albumin-to-creatinine ratio were in the normal range." (PMID 40002779, 2025). "Urinary albumin and creatinine levels, necessary for determining diabetic nephropathy, have not yet been evaluated in the literature." (PMID 39810396, 2025). "To conclude, cultured human CD34+ cells markedly improved urinary albumin excretion and attenuated pathological damage in a rat model of STZ-induced diabetic nephropathy, in spite of a hyperglycemic environment, highlighting their angiogenic and anti-inflammatory potential." (PMID 41294818, 2025).